LY6G6C (lymphocyte antigen 6 family member G6C)
Synonyms: C6orf24; G6C; NG24
Tractability: Antibody: UniProt places it where antibodies can reach, with high confidence; its Gene Ontology location is reachable by antibodies, with high confidence; UniProt predicts a signal peptide or a membrane-spanning region.
Gene: Protein-coding gene on chromosome 6 (31,718,648 to 31,721,746, reverse strand). Ensembl gene ENSG00000204421.
Subcellular location: Cell membrane
Pathways (Reactome):
Metabolism of proteins: Post-translational modification: synthesis of GPI-anchored proteins
Gene Ontology:
Molecular function: identical protein binding; protein binding
Cellular component: external side of plasma membrane; protein-containing complex; extracellular region; plasma membrane
Genetic constraint (gnomAD): Loss-of-function variants: 12 observed, 13.19 expected, observed/expected ratio (o/e) 0.91, 90% interval 0.58 to 1.47. The synonymous counts are far from expectation, so gnomAD's model fits this gene poorly and the ratio says little. Missense variants: 125 observed, 163.71 expected, observed/expected ratio (o/e) 0.76, 90% interval 0.66 to 0.89. Synonymous variants: 42 observed, 65.34 expected, observed/expected ratio (o/e) 0.64, 90% interval 0.5 to 0.83.
Homologues: Orthologues: chimpanzee LY6G6C (98% identical), macaque LY6G6C (98% identical), dog LY6G6C (87% identical), rabbit LY6G6C (86% identical), mouse Ly6g6c (85% identical), pig LY6G6C (85% identical), rat Ly6g6c (83% identical), guinea pig LY6G6C (72% identical).
Diseases named in the same sentence as LY6G6C in open-access papers:
LY6G6C is named in the same sentence as 5 diseases in open-access papers, as found by Europe PMC text mining. Sharing a sentence is not in itself a finding about the gene and the disease. The quoted sentences say what the papers report.
mucositis (1 paper, 2018). Mucositis is inflammation and damage of the mucous membranes lining the mouth and other parts of the gastrointestinal (GI) tract. "However, the expression of LY6G6C, which encodes a surface immunoregulatory protein, was upregulated before treatment in three cases of clinical none/mild mucositis, but not in four cases of ulcerative mucositis." (PMID 29338018, 2018).
LY6G6C also shares sentences with these, for which no sentence is quoted: endocrine disorder (1 paper); Infertility (1); prostate carcinoma (1); type 1 diabetes mellitus (1).